PMM2 (phosphomannomutase 2)
Diseases named in the same sentence as PMM2 in open-access papers (continued):
Sharing a sentence is not in itself a finding about the gene and the disease.
genetic diseases (6 papers, 2015 to 2025). "The identification of these variants is important for the correct diagnosis and counseling of parents and prospective parents and is common with the increasing awareness and attention paid by researchers to respective rare genetic diseases such as PMM2-CDG." (PMID 40225925, 2024). "PMM2-CDG, is the most common N-linked glycosylation disorder and subtype among all CDG syndromes, which are a series of genetic disorders involving the synthesis and attachment of glycoproteins and glycolipid glycans." (PMID 31727010, 2019). "Could small molecule drugs, pharmacological chaperones or drugs that affect proteostasis, be used to treat PMM2-CDG as it occurs for other genetic diseases ?" (PMID 26488408, 2015).
peripheral neuropathy (5 papers, 2019 to 2025). A disorder affecting the peripheral nervous system. "We demonstrate that epalrestat is the first small molecule activator of PMM2 enzyme activity with the potential to treat peripheral neuropathy and correct the underlying enzyme deficiency in a majority of pediatric and adult PMM2-CDG patients." (PMID 31636082, 2019). "Peripheral neuropathy is observed in almost all PMM2-CDG patients, so a therapeutic rationale for repurposing epalrestat for PMM2-CDG is compelling." (PMID 31636082, 2019). "Based on structure–activity relationships, we found that epalrestat, a generic diabetic peripheral neuropathy drug and the only safe aldose reductase inhibitor (ARI) approved for use in humans, is a first-in-class PMM2 enzyme activator." (PMID 31636082, 2019).
cancer (4 papers, 2019 to 2025). A tumor composed of atypical neoplastic, often pleomorphic cells that invade other tissues. "PMM2, a glycosylation enzyme, could influence immune cell function, while EPS8L2 has been linked to neurotoxicity in cancer therapeutics." (PMID 40170606, 2025).
infection (4 papers, 2013 to 2024). The state of being infected such as from the introduction of a foreign agent such as serum, vaccine, antigenic substance or organism. "Although these host glycosylation-based host-pathogen interactions are recognized as contributors to infection, discerning the exact impact of the glycosidic alterations in PMM2-CDG patients on their susceptibility to infections remains challenging." (PMID 38550576, 2024). "Neutrophils and monocytes are sensitive to PMM2 mutations, leading to abnormal glycosylation in immune receptors, which might potentially affect their affinity to their ligands, and contribute to infection." (PMID 24139637, 2013). "Moreover, uncontrolled NK cytotoxic activity could reduce the adaptive immune response during infection explaining at least partially the high susceptibility of PMM2-CDG patients to suffer from severe infections in the first years of life." (PMID 27415628, 2016). "PMM2-CDG is the most common N-glycosylation defect and shows an increased risk of recurrent and/or severe, sometimes fatal, infections in early life." (PMID 27415628, 2016). "Our results also suggest that neutrophils and monocytes are sensitive to PMM2 mutations, and relevant immunologic molecules could have abnormal proportion of mannose content with potential functional consequences that might contribute to explain the recurrent infections of PMM2-CDG patients." (PMID 24139637, 2013). "The aim of this study was to evaluate NK cell phenotype and cytotoxic function in PMM2-CDG patients which might help to explain their tendency to recurrent/severe infections in early age." (PMID 27415628, 2016). "An increased expression of glycosphingolipids, especially Gb3, in PMM2-CDG patients, might render them not only more susceptible to a broader range of infections but also make organs and tissues, typically less affected by microorganisms’ infection, more vulnerable." (PMID 38550576, 2024). "Therefore, the abnormal sialic acid profile in PMM2-CDG might contribute and indicate a disrupted microbiota, creating a conducive environment for pathogenic infections." (PMID 38550576, 2024). "Further studies must investigate if the abnormal glycosylation of CD16 in neutrophils and CD14 in monocytes of PMM2-CDG patients affects the function of these immune receptors, as suggested for CD16, which might potentially be implicated in the recurrent infections of these patients." (PMID 24139637, 2013). "Finally, using PMM2-CDG as a model, we point to links between abnormal glycosylation patterns in host cells and possibly favored interactions with microorganisms that may explain the higher susceptibility to infection." (PMID 38550576, 2024). "In the case of PMM2-CDG patients who present lower levels of sialylation, pathogenic bacteria may find the infection process easier because they do not need to use their neuraminidase to access internal glycan epitopes to initiate their adhesion process." (PMID 38550576, 2024).
tumor (4 papers, 2011 to 2026). "PMM2 is significantly upregulated in CRC tissues and cell lines, correlating with advanced tumor stages, lymphatic metastasis, and poor patient survival." (PMID 41786879, 2026). "KIFC3 mediates PMM2-driven glycolysis, as KIFC3 knockdown partially reverses PMM2-induced metabolic reprogramming and tumor growth in xenograft models." (PMID 41786879, 2026). "Only P4HA1, PMM2, and AGRN exhibited significant correlation with overall survival (OS), and the transcriptomic expression of P4HA1, PMM2, and AGRN was significantly upregulated in tumor tissues." (PMID 37428395, 2023).
adenocarcinoma (1 paper, 2016). A common cancer characterized by the presence of malignant glandular cells. "We however also observed one protein that was down-regulated in SCC while up-regulated in adenocarcinoma (VWA8) and vice versa 7 proteins showing the opposite behavior (FAK2, PMM2, K2C5, SMCA5, FAD1, DTX3L and CLU)." (PMID 26930711, 2016).
endocrinopathies (1 paper, 2025). "Glycoproteins are implicated in every endocrine axis, hence endocrinopathies are likely to occur in PMM2-CDG patients." (PMID 40771275, 2025).
myopathy (1 paper, 2024). A disease of the muscle in which the muscle fibers do not function properly. "Nevertheless, it is noteworthy to underlie that most patients in this study have GNE myopathy, a rare condition devoid of neurological dysfunction, which enables educational progression, compared with other severe forms of CDG (e.g., PMM2-CDG)." (PMID 38439013, 2024).
skeletal dysplasia (1 paper, 2021). Any Mendelian diseases that affects growth and development of the skeleton. "Contrary to PMM2-CDG, skeletal dysplasia was well characterized in other CDGs, including ALG12-CDG, ALG3-CDG, ALG9-CDG, ALG6-CDG, PGM3-CDG, CSGALNACT1-CDG, SLC35D1-CDG and TMEM165-CDG." (PMID 34441372, 2021). "Contrary to PMM2-CDG, all remaining CDG, including ALG12-CDG, ALG3-CDG, ALG9-CDG, ALG6-CDG, PGM3-CDG, CSGALNACT1-CDG, SLC35D1-CDG and TMEM-165, are characterized by well-defined skeletal dysplasia." (PMID 34441372, 2021). "Skeletal dysplasia is not a typical feature of PMM2-CDG but has been reported before." (PMID 34441372, 2021).
PMM2 also shares sentences with these, for which no sentence is quoted: Cerebellar ataxia (3 papers); dilated cardiomyopathy (3); cardiomyopathies (2); colorectal cancer (2); Encephalopathy (2); epilepsy (2); familial cancers (2); fructose intolerance (2); Hepatic cysts (2); Immune dysfunction (2); Infertility (2); neurodevelopmental disorder (2); 3-methylglutaconic aciduria (1); allergic reaction (1); Angelman syndrome (1); autism (1); autosomal dominant polycystic kidney disease (1); Birk-Landau-Perez syndrome (1); Blepharophimosis (1); brachydactyly (1); brainstem atrophy (1); cartilage disease (1); cerebral palsy (1); Cognitive impairment (1); craniofrontonasal syndrome (1); cryptorchidism (1); cutis laxa (1); diabetic neuropathy (1); dihydrolipoamide dehydrogenase deficiency (1); EARS disease (1).
A further 57 diseases each share a sentence with PMM2 in 1 paper.